ARRB2 (arrestin beta 2)
Diseases named in the same sentence as ARRB2 in open-access papers (continued):
Sharing a sentence is not in itself a finding about the gene and the disease.
autism (1 paper, 2025). Persistent deficits in social interaction and communication and interaction as well as a markedly restricted repertoire of activity and interest as well as repetitive patterns of behavior. "In summary, by using the BXD RI strains as a genetic reference population, we identified a significant association between Arrb2 and autism-related phenotypes across four brain regions: the amygdala, cerebellum, hippocampus, and prefrontal cortex." (PMID 40428426, 2025). "Future research could further explore the direct causal relationship among the three, if any and whether Arrb2 integrates cross-regional signaling to drive autism-related symptoms." (PMID 40428426, 2025). "Our investigation focuses on Arrb2, an emerging autism-risk candidate gene, to systematically dissect its pivotal role in orchestrating multi-brain-region gene regulatory networks and modulating autism pathogenesis." (PMID 40428426, 2025). "Elevated Arrb2 expression levels showed strong correlations with the severity of autism-related behavioral traits." (PMID 40428426, 2025). "Recent studies demonstrate that all these pathways are related to autism, supporting the importance of Arrb2 in autism pathogenesis." (PMID 40428426, 2025). "To further narrow down the Arrb2-interactors, we utilized the clinical data collected from human samples to identify differentially expressed genes between autism patients and controls." (PMID 40428426, 2025). "According to earlier studies conducted in our lab, a mouse model of autism generated by valproic acid (VPA) showed a substantial increase in Arrb2 expression." (PMID 40428426, 2025). "Using the Pearson correlation method, we identified significant correlations between Arrb2 expression and specific autism phenotypes." (PMID 40428426, 2025). "Furthermore, protein–protein interaction (PPI) network analysis, tissue correlation, functional relevance to autism, and differential expression identified eight downstream candidate genes regulated by Arrb2." (PMID 40428426, 2025). "Additionally, we analyzed the correlation between Arrb2 expression in each brain region and 424 autism-related phenotypes selected from GeneNetwork, based on a review article." (PMID 40428426, 2025). "This consistent change in expression patterns supports the hypothesis that Arrb2 contributes to autism pathogenesis by regulating Myh9, Dnmt1, and Brd4, although differently in different tissues." (PMID 40428426, 2025). "In this study, we used a systems genetics approach to explore the role of Arrb2 in autism." (PMID 40428426, 2025). "However, ASD arises from complex gene–environment interactions, so further investigation into Arrb2’s mechanistic role in autism pathogenesis is essential." (PMID 40428426, 2025). "To this end, we evaluated the expression variation in Arrb2 in four brain regions (amygdala, cerebellum, hippocampus, and prefrontal cortex) of BXD mice and its correlation with autism-related traits." (PMID 40428426, 2025). "Furthermore, Arrb2-correlated genes were used to explore potential signaling pathways, and subsequently identify downstream regulators that might be involved in the development of autism." (PMID 40428426, 2025).
cecum lymphoma (1 paper, 2024). An extranodal lymphoma that arises from the cecum. "Moreover, GATA3-AS1 stimulates the invasion and migration of EC cells by blocking miR-361, and promotes the activation of Arrestin beta 2 gene (ARRB2), which, among others, is involved in cecum lymphoma occurrence." (PMID 38893244, 2024).
COVID-19 (1 paper, 2021). A disease caused by infection with severe acute respiratory syndrome coronavirus 2. "NKTR and its PPI partners transcription initiation factor TFIID subunit 1 (TAF1), 40S ribosomal protein S14 (RPS14), and arrestin beta 2 (ARRB2) are differentially expressed in the PBMCs of COVID-19 patients." (PMID 34108016, 2021).
Cryptococcal meningitis (1 paper, 2022). Meningeal inflammation produced by cryptococcus neoformans, an encapsulated yeast that tends to infect individuals with acquired immunodeficiency syndrome and other immunocompromised states. "ARRB2, whose full name is arrestin beta 2, is also known as ARB2, ARR2, or BARR2, usually associated with diseases like WHIM syndrome and cryptococcal meningitis." (PMID 36284990, 2022).
cystic fibrosis (1 paper, 2018). Autosomal recessive disorder caused by pathogenic variants in the CFTR gene (cystic fibrosis transmembrane conductance regulator), which encodes a chloride and bicarbonate channel expressed in epithelial cells, and follow the diagnosis criteria. "ARRB2 was reported to be an important component of the mechanisms leading to cholesterol accumulation, which is a characteristic of epithelial cells associated with cystic fibrosis." (PMID 29853881, 2018).
cytomegalovirus infection (1 paper, 2017). A herpesvirus infection caused by Cytomegalovirus. "Arrb2 mediates the binding of Src homology-containing tyrosine phosphatases to KIR2DL1 to regulate the inhibitory signaling of NK cells, and Arrb2-deficient mice were less susceptible to cytomegalovirus infection compared with wild-type mice." (PMID 28525390, 2017).
endotoxemia (1 paper, 2011). "Indeed, Arrb2 regulates LPS-induced inflammatory response and endotoxemia, while Ntn1 can minimize inflammatory damage associated with ischemia-reperfusion injury." (PMID 22241984, 2011).
experimental autoimmune encephalomyelitis (1 paper, 2021). An autoimmune demyelinating disease of the central nervous system that is produced experimentally in animals by the injection of homogenized brain or spinal cord in Freund's adjuvant. "For example, in an experimental autoimmune encephalomyelitis (EAE) mouse model, ARRB1 knockout alleviates disease phenotypes, whereas ARRB2 deficiency exacerbates EAE symptoms." (PMID 33686256, 2021).
Huntington disease (1 paper, 2025). Huntington disease (HD) is a rare neurodegenerative disorder of the central nervous system characterized by unwanted choreatic movements, behavioral and psychiatric disturbances and dementia. "Furthermore, ARRB2 and PFKFB3 are promising biomarker candidates for Huntington’s disease (HD) due to their involvement in key pathological processes—ARRB2 in neuronal signaling and cell death, and PFKFB3 in glycolytic metabolism and energy stress." (PMID 40643497, 2025).
injury (1 paper, 2016). Damage inflicted on the body as the direct or indirect result of an external force, with or without disruption of structural continuity. "It is important to point out that the overall net effect of Arrb2 is to suppress pain or ‘arrest pain’ after inflammation and nerve injury." (PMID 27538456, 2016).
ischaemic stroke (1 paper, 2019). "In summary, we have found that NOD2 stimulation mediated robust and broad inflammatory response in microglia and ARRB2 negatively regulated NOD2‐induced inflammatory response following ischaemic stroke by combination with TRAF6." (PMID 30793522, 2019). "Taken together, ARRB2 emerged as an important control point in the integration of inflammatory responses mediated by NOD2, which may prove useful in the future development of new therapeutic approach for the treatment of ischaemic stroke." (PMID 30793522, 2019).
multiple myeloma (1 paper, 2025). "The role of ARRB2 in the pathogenesis of multiple myeloma (MM) has not been elucidated." (PMID 40214450, 2025).
myeloproliferative neoplasms (1 paper, 2020). A clonal hematopoietic stem cell disorder, characterized by proliferation in the bone marrow of one or more of the myeloid (i.e., granulocytic, erythroid, megakaryocytic, and mast cell) lineages. "ARRB2 is also critical in regulating signaling in another myeloproliferative disorder, primary myelofibrosis (PMF)." (PMID 33297302, 2020). "The crucial role of ARRB2 in the onset and maintenance of myeloproliferative neoplasms suggests that it could serve as a promising target for therapy." (PMID 33297302, 2020).
oral cancer (1 paper, 2020). "In SMAD4-positive OC-2 oral cancer cells, both ARRB2 and GIPC1 participate in TGFBR3-mediated inhibition of migration and invasion." (PMID 32471132, 2020). "In SMAD4-positive OC-2 oral cancer cells, TGFBR3-mediated suppression requires both of its cytoplasmic interacting partners ARRB2 and GIPC1." (PMID 32471132, 2020). "We next investigated whether ARRB2 or GIPC1 plays a role in SMAD4-independent, TGFBR3-mediated migration and invasion of oral cancer cells by knocking down ARRB2 or GIPC1 in TGFBR3-overexpressing CAL-27 cells." (PMID 32471132, 2020).
renal chromophobe cell carcinoma (1 paper, 2022). "A possible therapeutic target and prognostic marker for renal chromophobe cell carcinoma may be ARRB2." (PMID 36284630, 2022).
renal fibrosis (1 paper, 2017). A final common manifestation of a wide variety of chronic kidney diseases characterized by glomerulosclerosis and tubulointerstitial fibrosis. "Furthermore, we demonstrated that Arrb2−/− mice exhibited resistance to IR-induced renal fibrosis and renal function impairment following chronic alcohol exposure, and these effects were associated with attenuated GSK3β activation in the kidneys." (PMID 28642577, 2017). "Similarly, the chronic alcohol treatment did not exaggerate renal fibrosis at 14 days post-IR in Arrb2−/− mice." (PMID 28642577, 2017).
tumor (21 papers, 2017 to 2026). "Immunoassay showed that ARRB2 was associated with B cells, NK cells, endothelial cells, etc. and also connected with tumor-infiltrating lymphocytes (TILs)." (PMID 36284990, 2022). "Analysis of published human datasets shows that ARRB2 (gene encoding βArr2) expression is increased in RCC tumor compared to normal tissue and that high levels of ARRB2 correlate with worse patient survival." (PMID 29559707, 2018). "In vivo, experiments showed that STAT5B knockdown inhibited tumor growth by suppressing the expression of ARRB2 and phosphorylation of ERK1/2." (PMID 38341429, 2024). "The IHC was performed on tumor tissue from shSTAT5B and shNC groups, and the result indicated that the shSTAT5B downregulated the expression of ARRB2 and reduced the levels of pERK1/2 compared to the shNC group." (PMID 38341429, 2024). "Pathogenic variants of these genes were also identified, including tumor or posterior malformation in FZD4 (c.74G>T), ARRB2 (c.287A>C), and DACT1 (c.1561-1G>A) in humans and mice." (PMID 35008901, 2022). "While ARRB1 functions as an oncogene and positively regulates expression of stem cell markers, ARRB2 functions as a tumor suppressor and negatively regulates stem cell properties." (PMID 33297302, 2020). "This study identifies the tumor-promoting activities of ARRB2 and elucidates the regulatory mechanism of the METTL3-ARRB2-YAP/Raf axis in ICC, which may provide a novel prognostic biomarker and potential therapeutic target for human ICC." (PMID 41986296, 2026). "Furthermore, ARRB2 exhibited higher expression levels in tumor tissues compared to normal tissues, and its expression increased with a higher Gleason score, advanced T stages, and N stages." (PMID 38341429, 2024). "An inverse expression of ARRB1 and ARRB2 both significantly correlated with tumor metastasis." (PMID 37196048, 2023). "Moreover, it was found that ARRB2 was significantly downregulated in tumor versus normal tissues and presented with a higher frequency of CNV deletion." (PMID 38022584, 2023). "In our cell experiments, TNF-α and IL-6 were highly expressed in PRAD cell lines and positively regulated by ARRB2, suggesting that ARRB2 could affect PRAD tumor progression by regulating the expression of IFs." (PMID 36284990, 2022). "In summary, ARRB2 may consider as a target for therapeutic intervention against tumour development and metastasis in the studies of future." (PMID 36284630, 2022). "Importantly, expression of ARRB2 in patient tumor specimens inversely correlated with metastasis and gemcitabine + cisplatin treatment failure." (PMID 33297302, 2020). "CXCR7/Src/EGFR-mediated miyogenic signaling is negatively regulated by ARRB2, a tumor suppressor, which plays a crucial role in controlling CXCR7/EGFR-mediated tumor cell proliferation." (PMID 36276080, 2022). "Experimentally, we show that knockout of ARRB2 decreases rate of RCC cell proliferation and migration in vitro and xenograft tumor growth in animals." (PMID 29559707, 2018). "It was found that inhibition of ARRB2 expression reduced local and metastatic RCC tumor growth." (PMID 36284630, 2022). "We found that ARRB2, but not ARRB1, gene is significantly more expressed in ccRCC tumor compared to normal tissue." (PMID 29559707, 2018).
cancer (19 papers, 2012 to 2025). A tumor composed of atypical neoplastic, often pleomorphic cells that invade other tissues. "β‐arrestin 2 (ARRB2) is functionally implicated in cancer progression via various signaling pathways." (PMID 37443143, 2023). "Among the increased proteins following RBPMS knockdown, the two ARRB members—ARRB1 and ARRB2—are deregulated in many cancer types and have been linked to the inhibition of the senescence and growth as well as the promotion of the self-renewal, progression, and invasion of cancerous cells." (PMID 35008958, 2022). "In the case of G3 cancer, significant reduction in ARRB2 and DLG4 levels and overexpression of TERF2IP and SLC22A2 were observed." (PMID 34768458, 2021). "The authors developed chimeric aptamers by linking ARRB2 specific aptamers to aptamers that selectively bind the cancer cell specific cell membrane antigen nucleolin." (PMID 33297302, 2020). "They showed that the chimeric aptamers were internalized in cancer cells following binding to nucleolin and interacted with ARRB2 to inhibit ARRB2 mediated scaffolding and activation of ARRB2 mediated Wingless/Frizzled and Hedgehog/Smoothened signaling." (PMID 33297302, 2020). "Depletion of ARRB2 (in contrast to ARRB1) abrogated self-renewal of bcCML cancer stem cells and promoted differentiation as shown in in serial transplantation assays in mice." (PMID 33297302, 2020). "Since CXCR7 has been recognized as a marker for aggressive cancer there have been numerous attempts to develop CXCR7 inhibitors that could block ARRB2 recruitment." (PMID 37347559, 2023). "Furthermore, Arrb2 is involved in a variety of signaling pathways, including those that involve extracellular signal-regulated kinases (ERK) and protein kinase B (Akt).ARRB2 has been shown to be involved in the metastasis of a variety of cancer cells." (PMID 36284630, 2022). "We sought to dissect whether ARRB2 or GIPC1 plays a role in TGFBR3-dependent cancer-suppressive activity." (PMID 32471132, 2020). "However, the selective targeting of ARRB2 in cancer cells presents challenges because of its ubiquitous nature." (PMID 33297302, 2020). "However, recent attempts with ARRB2 specific aptamers that also specifically bind to cancer cells show promising results for specifically targeting ARRBs in cancer cells and or CSCs." (PMID 33297302, 2020). "Associations of ARRB2 expression in LTTs versus matched LNTs were characterized and Gene Set Enrichment Analysis (GSEA) was performed to determine whether ARRB2 expression was enriched in gene sets related to cancers, TLR signaling, and autophagy." (PMID 37443143, 2023). "The interactive analysis tool was applied to confirm the expression level of the eight DEGs (SPP1, TTK, MELK, FOXM1, LYN, ARRB2, COL6A3, and CCL21) in cancer and normal tissues." (PMID 33829064, 2021). "These 8 genes (SPP1, TTK, MELK, FOXM1, LYN, ARRB2, COL6A3, and CCL21) were further validated in more numbers of cancer tissue samples by quantitative real-time PCR (qRT-PCR)." (PMID 33829064, 2021). "ARRB2 and JAK3 were highly expressed in T cells, while PTK2 and ACTG1 were mainly enriched in the 'Cancer cluster." (PMID 32549766, 2020). "Overexpression of ARRB2 induced expression of ENT1, which promotes influx of Gemcitabine into cancer cells, and was also shown to inhibit conversion of gemcitabine into inactive metabolites by inhibiting the enzyme Cytidine Deaminase (CDA)." (PMID 33297302, 2020). "Many cancers are driven from CSCs and both ARRB1 and ARRB2 were shown to be crucial in regulating CSC self-renewal." (PMID 33297302, 2020). "Moreover, our network analysis indicated alterations in MAPK/ERK and Jun-N-terminal kinase pathways and the potential important role of PAX3, VCAN, ARRB2, NR1H2, and ITGA5 that may provide insights into mechanisms involved in longevity and regeneration that are distinct from cancer." (PMID 22477361, 2013).
infection (5 papers, 2014 to 2025). The state of being infected such as from the introduction of a foreign agent such as serum, vaccine, antigenic substance or organism. "The infection progression associated with essential epigenetic modifications in two strains of C. albicans such as ARRB2, CDH1, HSP90B1, EGFR and ERBB2, and host miRNA repressing on pathogens genes are mostly identified in core HPCNs by our systems biology approach." (PMID 30769958, 2019). "We further compared the survival rates between WT and Arrb2−/− mice after infection with HSV-1 or VSV and observed that Arrb2−/− mice were more susceptible to HSV-1 or VSV and suffered higher mortality than their WT counterparts." (PMID 33243993, 2020). "Conversely, in C. albicans SC5314 infection, ARRB2 with the same epigenetic modification triggers different proteins such as SSR4 and C18orf8." (PMID 30769958, 2019). "SA2 infection negatively regulated expression of genes like b-arrestin (ARRB2), integrinAε (ITGAE), hemolytic complement (HC), lymphocyte protein tyrosine kinase (LCK) that are involved in pathogen clearance or induction of immune response." (PMID 25075227, 2014). "After the infection of mice with HSV-1, the expression levels of Ifnb, Ccl5, and Isg15 were significantly lower in the spleens, livers, and lungs of Arrb2−/− mice than in those of WT mice." (PMID 33243993, 2020).
cardiac diseases (2 papers, 2014 to 2018). "The Arrb2/miR-155/GSK3β pathway may be a new mechanism with implications for treatment of heart disease." (PMID 24974728, 2014).
neurodegenerative disease (2 papers, 2024 to 2025). A disorder of the central nervous system characterized by gradual and progressive loss of neural tissue and neurologic function. "ARRB2, known to regulate apoptosis and cell survival, plays an essential role in processes disrupted in neurodegenerative diseases like AD, PD and FTD." (PMID 39980027, 2025).
cardiovascular diseases (1 paper, 2014). "We suggest a loop pathway between miR-155 and Arrb2, which explains the mechanism for its participation in regulating cardiovascular diseases." (PMID 24974728, 2014).
liver (1 paper, 2023). "However, when ARRB2 was silenced, the downregulation of liver fibrosis- and inflammation-related genes was not obvious." (PMID 36983568, 2023).